BIRC5 (baculoviral IAP repeat containing 5)
Diseases named in the same sentence as BIRC5 in open-access papers (continued):
Sharing a sentence is not in itself a finding about the gene and the disease.
cancer (continued). "In addition, a cluster of genes associated with epithelial and cancer cells (for example, CDH1, EPCAM, BIRC5 and CD276) was significantly downregulated in resected tumors with nivolumab/relatlimab-induced MPR." (PMID 38689060, 2024). "Moreover, interactions between BIRC5 and other cancer-related proteins, including cell cycle regulators, apoptosis inhibitors, and DNA repair enzymes, underscore its significance in tumor biology." (PMID 39703228, 2024). "Future cancer treatments might involve targeted inhibition of BIRC5 to prevent tumor cell proliferation and improve patient outcomes." (PMID 39703228, 2024). "Moreover, these cells expressed the CDC20 gene, encoding cell division cycle protein 20 homolog, which can function as an oncoprotein, and BIRC5, which inhibits apoptosis; both promote cancer progression, and are poor prognostic markers in cancer patients." (PMID 39405604, 2024). "KEGG pathway analysis highlights that BIRC5 may contribute to cancer through its impact on the PI3K/Akt, MAPK, and NF-kB signaling pathways, all of which are crucial for tumor growth, survival, and metastasis." (PMID 39703228, 2024). "BIRC5 exhibits a significantly elevated level in nearly all types of cancer." (PMID 38832035, 2024). "For example, detecting BIRC5 levels in cancers like breast, lung, and stomach could help predict patient outcomes and inform tailored therapeutic strategies." (PMID 39703228, 2024). "However, the precise mechanisms by which BIRC5 influences various cancer types, particularly its expression across various molecular and immune subtypes and its clinical relevance, remain incompletely understood and warrant systematic investigation." (PMID 39703228, 2024). "Notably, our pan-cancer analysis further strengthens the potential of BIRC5 as an immunotherapy target, particularly in cancers with significant immune evasion mechanisms." (PMID 39703228, 2024). "In this regard, decreasing BIRC5′s oncogene expression might correct the resistance to various therapy regimens and serve as a promising independent cancer survival marker." (PMID 38276004, 2024). "Thus, these molecules have the potential to be valuable new agents for cancer treatment since they can effectively inhibit the enzymatic activity of the BIRC5 protein." (PMID 39397921, 2024). "During the process of tumor formation, alterations in both the quantity and quality of BIRC5 may initiate an immune response, resulting in the production of autoantibody in individuals with cancer." (PMID 38832035, 2024). "Survivin/BIRC5 inhibits apoptosis of tumor cells, and therefore supports cancer cell survival." (PMID 37439806, 2024). "K-M curves showed that only BIRC5 high expression group were associated with poor OS in PAAD, and BIRC5 has no prognostic value in other cancers." (PMID 37679418, 2023). "The BIRC5 gene plays a key role in preserving the transformation of normal cells into cancer cells." (PMID 37408277, 2023). "BIRC5, also known as survivin, is an anti-apoptotic protein that is common in cancer." (PMID 37509353, 2023). "Our previous studies suggest that BIRC5 may be responsible for the pluripotency state of stem cells, and its high expression may also be responsible for the de-differentiation of cancer cells." (PMID 36768802, 2023). "In order to understand the connections between BIRC5, HIF1A, and FLT4 expression and specific immune cells, we conducted a correlation analysis between these oncogenes and markers of cancer-associated fibroblasts (CAFs), considering the influence of sample purity." (PMID 37509650, 2023). "Loss and gain of function studies showed the critical role of BIRC5 in cancer growth." (PMID 38203388, 2023). "Therefore, inhibition of BIRC5 results in anti-cancer effects in cell lines of the three RCC subtypes." (PMID 38203388, 2023).
cancer (continued). "BIRC5, also known as survivin, acts as an anti-apoptotic protein that hinders apoptosis-related signaling pathways, thereby promoting cell proliferation and facilitating cancer progression." (PMID 38124072, 2023). "The results suggest that the synergistic effect of the cell-cycle-related genes UBE2C, PLK1, and BIRC5 may promote the development of pan-cancer by affecting cell metabolism." (PMID 37958642, 2023). "Moreover, Birc5 is overexpressed in aggressive cancers where its presence correlates with increased resistance to chemotherapy and irradiation." (PMID 35836253, 2022). "Given that overexpression is positively correlated to cancer development and aggressiveness, these data strongly imply that BIRC5 may mediate carcinogenesis." (PMID 36358602, 2022). "Finally, we found that BIRC5 was correlated with sensitivity to diverse drugs in the cancer therapeutic response portal database, with some positive and some negative correlations." (PMID 35309512, 2022). "This treatment may be a useful treatment for other kinds of cancers that have high expressions of BIRC5 and EphA2." (PMID 36439089, 2022). "The results of this study suggest that BIRC5 may be involved in drug resistance of cancer cells by enhancing EMT." (PMID 35715750, 2022). "There have been a few studies that have focused on BIRC5 in various cancers, including BC." (PMID 36358602, 2022). "These date suggest that BIRC5 may not only operate as an oncogene but also as a promising predictive biomarker and possible therapeutic target in cancer." (PMID 36358602, 2022). "Both BIRC5 and BIRC6 have been linked to cancer in other publications." (PMID 35428183, 2022). "We used the TGCA database to examine the expression of BIRC5 in all cancers." (PMID 35309512, 2022). "Moreover, survivin/BIRC5, overexpressed in cancers and a prognostic marker of several cancers, was highly reduced in the SMAC-KO cells." (PMID 36185255, 2022). "Furthermore, YM155, a selective BIRC5 inhibitor, has been found to possess potent antitumor activities against numerous cancers including DLBCL xenografts and can determine objective responses in some DLBCL patients as a single agent." (PMID 35053500, 2022). "We further compared the relative expression of these molecules in 14 cancer types containing paired tumor and normal samples and found that approximately half of the autophagy regulators showed elevated expression in different cancers, including BIRC5, RIPK2, MET, ITGA6, BCL2L1, CASP4, etc.." (PMID 36261830, 2022). "One of the most critical proteins in the development of various cancers is BIRC5." (PMID 35928368, 2022). "There are several in vitro studies that show how BIRC5 overexpression or silencing could affect cancer cell lines." (PMID 35331169, 2022). "Moreover, emerging studies had reported that BIRC5 had an abnormally increased expression in diverse cancer tissues and played a critical role in the malignant progression of tumors." (PMID 35461228, 2022). "Survivin (encoded by the BIRC5 gene) is an anti-apoptotic protein often over-expressed in various cancer types and absent or little-expressed in normal cells." (PMID 34065488, 2021). "BIRC5, a member of the human inhibitors of apoptosis proteins (IAPs) family is one of the most studied molecular and therapeutic targets in various type of cancer s." (PMID 34804966, 2021). "In recent years, studies have shown that BIRC5 may be a universal target antigen for anti-cancer immunotherapy." (PMID 33431968, 2021). "BIRC5 or Survivin is a well-studied anti-apoptotic protein promoting PC and cancer metastasis." (PMID 33498739, 2021). "However, methylation profiles have a significant influence in the regulation of the expression of BIRC5 in many cancers." (PMID 34685742, 2021). "Notably, BIRC5 (survivin) is a client protein of Hsp90 chaperone and results downregulated upon Hsp90 pharmacological inhibition in cancer cells." (PMID 33413657, 2021).
cancer (continued). "Therapies targeting BIRC5 are considered as promising therapies for the treatment of various cancers owing to the abnormally high expression of BIRC5 during the carcinogenic process of various types of cancers." (PMID 34490029, 2021). "BIRC5 has an immunohistochemistry staining pattern similar to cancer markers such as Ki67." (PMID 34503306, 2021). "BIRC5 regulates cancer development by inhibiting cell apoptosis and inducing cell proliferation." (PMID 34289837, 2021). "As cancer cells undergo active division, perhaps the up regulation of genes like BIRC5, CENPF could be a direct consequence of active mitosis." (PMID 33828156, 2021). "The abnormal expression of BIRC5 is related to the malignant transformation of the cancer cell." (PMID 34746309, 2021). "According to the analysis in TIMER, aberrant expression of BIRC5 may alter cancer microenvironment and immune response, thus impact on the overall clinical outcome." (PMID 34804966, 2021). "BIRC5 is an abundantly expressed protein in both healthy and cancer cells." (PMID 34503306, 2021). "BIRC5 is particularly concentrated in cells actively undergoing mitosis in the G2/M phase of the cell cycle, although it is present in some quantity in cell nuclei of cancer cells at all times." (PMID 34503306, 2021). "Aberrant expression of BIRC5 in cancers have been found to facilitate cancer progression." (PMID 34804966, 2021). "BIRC5 (also known as survivin) has been proven to regulate migration and invasion of a variety of cancer cells, including cervical cancer, and is a well-known target for cancer therapy." (PMID 34030694, 2021). "We show that BIRC5 is a promising independent cancer survival marker." (PMID 34064473, 2021). "In this primary culture, a unique transcription of the CXCL12 and FAP genes was observed; by pattern of gene expression, they corresponded to fibroblasts, and the SURV promoter of the cancer-specific gene Survivin (BIRC5) worked in it worse than in cancer cells." (PMID 33804861, 2021). "miR-198 overexpression could significantly reduce cell viability and promote cell apoptosis by targeting BIRC5; furthermore, it can decrease cancer cell migration and invasion, whereas BIRC5 coexpression could reverse this effect." (PMID 34289837, 2021). "Therefore, in the current study involving GBM, we started with the study of BIRC5 (one of the rare genes differentially expressed in normal and cancer cells) and CXCR4 (gene involved in the survival and proliferation of CSCs)." (PMID 34685742, 2021). "Taken together, these data indicate that the disruption of BIRC5 interactions may hold promise in cancer therapy." (PMID 33917186, 2021). "In detail, Dasatinib was conjugated with a specific oligonucleotide complementary (anti-sense) to an mRNA overexpressed in cancer cells (human BIRC5 mRNA, highly expressed in many cancers, and AML1/ETO translocation, present with high frequency in acute myeloid leukemia)." (PMID 34207175, 2021). "Overexpression of BIRC5 in cancer may inhibit this apoptotic checkpoint and favor aberrant mitosis of transformed cells." (PMID 33431968, 2021). "BIRC5 gene (survivin) that encodes for BIRC5 protein, which is the smallest member of the inhibitor of apoptosis protein (IAP) 26, is strongly expressed in fetal tissues and typical human cancer cells." (PMID 33995625, 2021). "Survivin, encoded by the BIRC5 locus is an essential protein for cell division and can inhibit cell death in most, if not all cancers including high-risk NBs." (PMID 34945759, 2021). "Birc5 was originally identified and characterized in human cancers." (PMID 32155884, 2020).
cancer (continued). "Six of these validated genes (BIRC5, MK167, MMP9, PLOD2, and TOP2A) have previously been implicated ccRCC,21, 22, 23, 24, 25, 26, 27, 28, 29, 30, 31, 32, 33, 34 while the others have been implicated in other cancers." (PMID 32986937, 2020). "In addition, it has been previously shown that BIRC5 is overexpressed in a subset of breast stem cancer cells." (PMID 32183150, 2020). "The expression of Birc5 has been detected in various normal tissues such as the liver, arterial muscle, stomach, brain, ovary, testes, and uterus, though at lower levels than in cancers." (PMID 32155884, 2020). "It has been reported that BIRC5 plays a crucial role in many cancers." (PMID 33457419, 2020). "It is important to note that YY1 binds the BIRC5 promoter in both cancer and normal cell lines." (PMID 32899428, 2020). "Together, these findings indicate that BIRC5 may not only function as an oncogene, but also as a promising predictive biomarker and potential therapeutic target in cancer." (PMID 32043523, 2020). "Univariate analysis revealed that high-level BIRC5, recurrence/metastasis, new tumor event after initial treatment, advanced TNM stage, and person neoplasm cancer status with tumor are potential risk factors significantly associated with OS in TN adenocarcinoma patients (all P < 0.05)." (PMID 31093306, 2019). "The synergy of these approaches could overcome the concomitant expression of H3K27ac and H3K27me3 to predominantly favor repression of the Birc5 promoter, resulting in a more sensitive induction of apoptosis in cancer." (PMID 30909651, 2019). "BIRC5 has been shown to inhibit cell apoptosis yet promote cell proliferation in human cancers." (PMID 31250518, 2019). "In combination with FEC/TE, I2 treatment exhibited a synergic effect on cancer cell apoptosis and impaired expression of chemoresistance markers (BIRC5 and HIF1A) as well as changes in the expression of specific EMT markers (increased E-cad expression and decreased Vimentin expression)." (PMID 31319484, 2019). "As predicted, knockdown of CCND3 or BIRC5 inhibits the growth of cancer cells." (PMID 29416000, 2018). "In addition, its upregulation also suppresses the apoptosis of the cancer cells by decreasing B‐cell lymphoma 2 (BCL2) and increasing BCL2‐associated X protein (BAX), and baculoviral IAP repeat containing 5 (BIRC5) transcription." (PMID 29473345, 2018). "These include a number of matrix metalloproteinases that disrupt the extracellular matrix and activate TGF proteins, promoting cancer cell invasion and metastasis, as well as cell survival proteins such as survivin (BIRC5), which is strongly upregulated in many human cancers." (PMID 30325954, 2018). "Up regulation of several IAPs like NAIP (BIRC1), X-linked IAP (XIAP, BIRC4), Survivin (BIRC5), c-IAP1 (BIRC2), c-IAP2 (BIRC3), Apollon (BRUCE, BIRC6), Livin/MLIAP (BIRC7) and IAP-like protein 2 (BIRC8) have been reported in several cancer cells as well as in serum from cancer patients." (PMID 29464049, 2018). "BIRC5 codifies for a protein which is vital for the growth and survival of cancer cells." (PMID 29330624, 2018). "Moreover, STAT3 is found to be active in many human cancers, and crucially involved in induction of BIRC5/survivin expression, and has been observed to correlate with increased invasion, metastasis and chemo-resistance in cancer." (PMID 30481203, 2018). "Furthermore, four key genes highly involved in ‘pathways in cancer,’ BIRC5, E2F1, CCNE1 and CDKN2A, were bioinformatically validated and selected out for further diagnostic and prognostic tests." (PMID 28316892, 2017). "IAPs, in particular BIRC5, have been described as therapeutic targets in the treatment of cancer." (PMID 27074575, 2017).
cancer (continued). "In previous studies, BIRC5 has been reported in several malignant tumors." (PMID 29190974, 2017). "A biochemical examination of PL-induced cell death indicated that it represses various anti-apoptotic proteins including B-cell CLL/lymphoma 2 (BCL2), baculoviral IAP repeat-containing 5 (also known as survivin) and X-linked inhibitor of apoptosis (XIAP) in cancer cells." (PMID 25984950, 2015). "BIRC5/SURVIVIN is one of the most frequently over-expressed genes in all types of cancer." (PMID 25296978, 2014). "Although the down-regulation of BIRC5 expression by anti-BIRC5 agents can inhibit the growth of cancer, tumors consistently obtain growth capabilities in later stages, demonstrating that this treatment approach remains poorly characterized and requires further study." (PMID 23433354, 2013). "However, when the anti-BIRC5 agent is used alone, the long-term efficacy remains uncertain and is variable for different types of cancers; tumors have always relapsed and regrown in later stages after treatment." (PMID 23433354, 2013). "It was reported that BIRC5 knockdown might inhibit proliferation and induce apoptosis in cancer cells." (PMID 22713668, 2012). "BIRC5 is up-regulated in almost all human tumors and its functional involvement, in apoptosis as well as in proliferation, leads to consider it as a new target for cancer treatment." (PMID 21858171, 2011). "It has been reported that BIRC5 was markedly over-expressed in a broad range of human cancers." (PMID 21304814, 2011). "The level of BIRC5 correlates with the degree of dysplasia and is highest in carcinomas." (PMID 21776270, 2011). "In addition, BIRC5 could promote cancer progression by modulating PD-L1 expression and inducing tumour immune evasion." (PMID 40591061, 2025). "For instance, the Wilcoxon test did not detect a change in expression of cancer-associated genes Tacc3 and Birc5, which had more than 0.2 counts/cell in both groups of neurons, more than 3-fold change in expression, and FDR-adjusted p < 10−5 in the weighted-t-test/χ2-test combination." (PMID 41473326, 2025). "Consequently, BIRC5 could be integrated into cancer screening and prognosis assessment to enable more individualized and precise treatments." (PMID 39703228, 2024). "Thus, BIRC5 was found to have a close correlation with cancer progression." (PMID 38203388, 2023). "Notably, BIRC5, which has robust anti‐apoptotic capabilities, is overexpressed in numerous cancers." (PMID 38112021, 2023). "Finally, we examined BIRC5 expression in other cancers and determined whether BIRC5 might be a widespread tumor marker." (PMID 36358602, 2022). "Finally, BIRC5 is found in cancer-derived exosomes, where it may play a role in disease progression." (PMID 34503306, 2021). "In addition, the increase of BIRC5 indicates multi-drug resistance in various type of cancer." (PMID 34804966, 2021). "High amounts of BIRC5 could therefore be undesirable in stressed cancer cells." (PMID 33671869, 2021). "This indicates that BIRC5/Survivin modification could be therapeutic against cancer." (PMID 34371830, 2021). "Interestingly, BIRC5 was significantly over-expressed in 21 human cancers." (PMID 31964418, 2020). "Additionally, BIRC5 negatively modulates the protein stability of ATG7 and physically binds to the ATG12–ATG5 conjugate, thereby preventing formation of the ATG12–ATG5–ATG16L1 protein complex in human cancer and suggesting that BIRC5 can directly regulate autophagy in cancer cells." (PMID 33109128, 2020). "However, cancer is a result of highly complex molecular mechanisms, and more experimental studies are necessary to clarify the cell cycle-related signaling for TN adenocarcinomas in the context of BIRC5." (PMID 31093306, 2019).